TNF (tumor necrosis factor)
Diseases named in the same sentence as TNF in open-access papers (continued):
Sharing a sentence is not in itself a finding about the gene and the disease.
depression (continued). "Pro-inflammatory cytokines such as Interferon-gamma (IFNγ) and Tumor necrosis factor α (TNFα) might contribute to the development of depressive disorder by regulating neuronal excitability, synaptic transmission, synaptic plasticity, and neuronal survival." (PMID 34206086, 2021). "Using data from a prospective study of Korean patients with depressive disorders receiving stepwise antidepressant treatment, we investigated the effects of the baseline serum TNF-α (sTNF-α) level on antidepressant treatment outcomes including 12-week and 12-month remission and 24-month relapse." (PMID 34475376, 2021). "However, a recent meta-analysis of eight studies investigating pro-inflammatory cytokines in children and adolescents with depressive disorders revealed only a trend toward significantly higher levels of peripheral TNF-α ⁠." (PMID 32495042, 2021). "Pro-inflammatory cytokines such as IFNγ and TNFα might induce the development of depressive disorder by affecting neuronal excitability, synaptic transmission, synaptic plasticity, and neuronal survival." (PMID 34206086, 2021). "Studies confirm that depressive disorders, in the absence of other physical comorbidities, are associated with increased levels of various pro-inflammatory cytokines, including tumor necrosis factor alpha (TNF-α) and interleukins (ILs)." (PMID 33920992, 2021). "Depression-like behavior in rodents correlates with increased levels of pro-inflammatory cytokines: interleukin-1β (IL-1β), interleukin-6 (IL-6), and tumor necrosis factor α (TNFα), and decreased levels of anti-inflammatory interleukin-10 (IL-10)." (PMID 32188010, 2020). "In addition, supraspinal TNF-α has been regarded as the common link between chronic pain and the comorbid depression." (PMID 32299452, 2020). "Considering that the incidence of depression is polygenic and it relates to many factors, such as race, environment, gender, and age, the connection between the SNP of TNF‐α G‐308A gene and depression is still required to be set forth by large sample case–control studies." (PMID 32307924, 2020). "Much of the interest in inflammation and depression has been focused on cytokines, which mediate the innate immune response, including tumor necrosis factor alpha (TNF-α), and IL-6, which appears to be one of the most reliable peripheral biomarkers in major depression." (PMID 33324599, 2020). "TNFα may therefore be a useful lead marker for the study of depression treatment effects on immune system excitability." (PMID 33240126, 2020). "Another review noted that vitamin D supplementation can robustly reduce TNF-α and IL-6, but not other cytokines, yet TNF-α and IL-6 were the two cytokines that were the most robustly associated with depression in a meta-analysis." (PMID 32629761, 2020). "Neuroinflammation initiated by TNF-α located at the hippocampus could be a common mechanism between pain and depression or memory deficits." (PMID 32241292, 2020). "Unfortunately, TNF‐α G‐308A gene polymorphism also did not affect the susceptibility of different types of depression." (PMID 32307924, 2020). "In addition, TNF-α was shown to disrupt blood–brain barrier (BBB) integrity in a mouse model of depression and in patients with T2DM, and to increase BBB permeability, which is restored by treatment with anti-inflammatory drugs." (PMID 32971941, 2020). "Enhanced inflammation reported in the melancholic subtype in certain studies (e.g., elevated CRP, IL-6, TNF-α) could reflect the characteristics of the study cohort (e.g., patients with more severe symptoms of depression, inpatient)." (PMID 33255237, 2020). "Therefore, the question is, can TNF-α/NF-κB signaling act as a promotor in the mechanism of comorbidities of pain such as depression or memory deficits?" (PMID 32241292, 2020). "Cerebral ischaemia leads to the production of increased proinflammatory IL-1β and TNF-α, which could further result in decreased 5-HT production, additionally promoting depression." (PMID 32184899, 2020).
depression (continued). "This dose-dependent relationship may also affect the relationship between TNF-α and the severity of the depression and, in this study, the BDI values." (PMID 32528052, 2020). "Moreover genome-wide association stud (GWAS) analysis showed that various proinflammatory cytokines including IL-1β, TNF, and CRP have been linked to depression and response to treatment." (PMID 32380663, 2020). "IL-1β, IL-6, and TNF-α are the most generally demonstrated proinflammatory cytokines in depression." (PMID 32596383, 2020). "Activated microglia synthesizes IL-6 and TNF-α, as antineurogenic signals, which can interact directly with neural progenitor cells and determine a decrease in neurogenesis also on the brain structures that regulate emotions in depression." (PMID 32545890, 2020). "In addition, various studies demonstrated increased serum levels of TNF-α, IL-1β, and IL-6 in patients with depression." (PMID 32184729, 2020). "In addition, IL-6 is involved in neurogenesis, neural mediation, and TNF-α plays a major role in the brain’s immune response and is an important indicators for depression." (PMID 32922291, 2020). "Astrocyte activation could result in the release of inflammatory cytokines, including IL-1β, IL-6, and TNF-α, which could promote the symptoms of depression." (PMID 32321532, 2020). "TNF-α is another pro-inflammatory cytokine related to the development of depression." (PMID 32321532, 2020). "Elevated TNFα in depression may be responsible for lesser efficacy of conventional antidepressants, which would suggest future tailoring therapy to individual cytokine profiles." (PMID 32992983, 2020). "IL-6, TNF-α, and corticosterone are highly expressed in patients with anxiety and depression." (PMID 32158447, 2020). "In addition, in our reserpine-induced animal model of depression, levels of IL-1β, IL-6, and TNF-α were significantly higher than those in control mice." (PMID 32754030, 2020). "Furthermore, some reports pointed the elevation of inflammatory cytokines [mainly interleukin-1 (IL-1), interleukin-6 (IL-6), and tumor necrosis factor-α (TNF-α)] in depression." (PMID 33329109, 2020). "Furthermore, the concentrations of interleukin-6, C-reactive protein, and tumor necrosis factor-α are increased in patients with CHD with co-morbid depression." (PMID 33584362, 2020). "Nevertheless, RA therapeutics inhibiting pathogenetic pro-inflammatory cytokines like tumor necrosis factor (TNF) and interleukin-6 (IL-6) alleviate symptoms such as depression and anxiety and were linked to a reduced risk of future neurodegeneration in RA patients." (PMID 33362800, 2020). "Also, a randomized controlled trial revealed that TNF-α inhibitors (TNFi) can improve depressive symptoms in patients with treatment-resistant depression and increased inflammatory markers." (PMID 32993799, 2020). "In addition, tumor necrosis factor-alpha (TNFα), a cytokine that is increased in heart failure, can biologically increase the incidence of depression." (PMID 33339355, 2020). "This raises the possibility that TNF-α, which is activated in several somatic diseases and leads to somatization, may also be involved in the development of depression." (PMID 33364982, 2020). "However, there is increasing evidence of a bi-directional relationship between inflammatory markers, such as IL-6 and TNF-α, with depression." (PMID 31899521, 2020). "An experiment shows that among 37 outpatients with major depression and 48 healthy controls, increased pain sensitivity (by pressure pain thresholds test) in depression may link to increased TNF-α concentration." (PMID 33144854, 2020). "Furthermore, our findings of increased mean levels of CRP, IL-6, IL-12 and TNF α in depression replicate previous meta-analytical findings; the same can be said of no changes in levels of TGF β." (PMID 32113908, 2020). "In addition, PI3k-Akt pathway controlled BDNF (such as IL-6, TNF-α) to reverse depression-like behavior in a neurotrophic and neuroprotective way." (PMID 32997725, 2020).
depression (continued). "In the same sample, we also find that blood levels of CRP, IL-3, IL-6, IL-12, IL-18, sIL-2R and TNF α are significantly elevated in patients with depression with medium-large effect sizes (range 0.54–1.97), and that these findings are robust to a range of potential confounds and moderators." (PMID 32113908, 2020). "The dysregulation of the α2-AR pathway may contribute to the release of pro-inflammatory cytokines, such as tumor necrosis factor-α (TNF-α), interleukin-1 (IL-1) and IL-6, thus increasing the susceptibility to depression." (PMID 33551951, 2020). "The results of this study suggested that the serum TNF-α levels were sensitive to the depressive state, supporting the cytokine theory in the inflammatory hypothesis for the development of depression." (PMID 33364982, 2020). "Increased levels of proinflammatory biomarkers (including CRP, IL-6, and TNF-α) were found in patients with depression, whereas NSAIDs treatment significantly inhibited the inflammatory response and reduced the suicidal ideation and depression symptoms in depressed patients." (PMID 32522211, 2020). "Correlations within groups showed that the severity of depression determined by the BDI-FS was positively associated with TNF-α in depressed, but not in non-depressed participants." (PMID 32528052, 2020). "Further, subgroup analyses showed that the TNF‐α G‐308A gene polymorphism also did not confer susceptibility to poststroke, late‐life, maternal, or major depression." (PMID 32307924, 2020). "Thus, there is evidence in different studies of TNFα’s role in depression, and we postulate a similar role for TNFα in relation to MDD in adolescents as evidenced by elevated levels in our study." (PMID 33192676, 2020). "However, in a recent meta-analysis evaluating peripheral chemokine and cytokines in depression, while the majority of studies found positive relationships, lower concentrations of TNF-α and IFN-γ were also observed." (PMID 32164571, 2020). "Additionally, TNF-α/NF-κB signaling has also been shown to be involved in the development of depression and the regulation of memory." (PMID 32241292, 2020). "Increased, unchanged, and decreased levels of TNF-α have been reported in depression." (PMID 33364982, 2020). "The cooccurrence of chronic pain and depression is intimately related to increases in TNF-α, IL-1β, and IL-6 in target structures such as the PFC, ACC, amygdala and hippocampus, emphasizing the involvement of glial activation in limbic regions involved in pain and depression processing." (PMID 32849076, 2020). "Uguz and colleagues showed that psychiatric disorders were identified less frequently in patients with RA receiving anti-TNF compared to patients who did not receive such medications, and a significant decrease in depression has been reported in patients with AS who receive anti-TNF." (PMID 32072134, 2020). "TNF-α plays an important role in the development of depressive disorders." (PMID 31215856, 2020). "Meta-analytic results have shown significantly higher concentrations of the pro-inflammatory cytokines TNF-α and IL-6 in depressed subjects compared with control subjects, strengthening the evidence that depression is accompanied by activation of the inflammatory response system." (PMID 31039822, 2019). "Several lines of evidence support the efficacy of TNF-α inhibitors in the treatment of depression." (PMID 30804748, 2019). "Treatment with the TNF-α antagonist, etanercept, or the cytokine synthesis inhibitor, pentoxifylline, prevents/reverses the depression-like behaviour consistent with the concept that neuro-inflammation contributes to depression-like behaviour in rats with HF." (PMID 31233508, 2019). "Furthermore, elevated serum levels of several pro-inflammatory cytokines, such as TNFα, IL-1β, and IL-6, have also been detected in patients with depression." (PMID 31312123, 2019). "The proinflammatory mediators, TNF-α and IL-6, were related to the etiologies of depression." (PMID 30823679, 2019).
depression (continued). "Patients with depression may have hyperalgesia due to the effect of pro-inflammatory cytokines, such as TNF—α, that could reduce the pain threshold both in the brain and in the dorsal root ganglia." (PMID 31765424, 2019). "An increase in proinflammatory cytokine levels including TNFα have occurred in patients who have suffered from a myocardial infarction and is associated with disruption of the BBB integrity in animal models and elevated rates of depression." (PMID 31379879, 2019). "Meta-analyses of randomized controlled trials have indicated that non-steroidal anti-inflammatory drugs (NSAIDs) and anti-tumor necrosis factor (TNF) treatments may improve the symptoms of depression." (PMID 31505850, 2019). "Although the release of pro-inflammatory cytokines can contribute to the development of depression-like behavior, TNF-α in particular is receiving considerable attention due to its prominent roles in promoting inflammation and its dampening effects on synaptic plasticity." (PMID 30804748, 2019). "In addition, the expression of IL-1β, IL-6, and TNF-α was also increased in postmortem brain samples from suicide victims that suffered from depression." (PMID 31068207, 2019). "Preclinical studies corroborate the role of TNF-α in depression-like behavior." (PMID 30804748, 2019). "It was found that SNS may up-regulate CYP1A2, CYP2D1, CYP2E1, and CYP3A2 activity to reduce IL-6 and TNF-α expression, as well as up-regulation of BDNF and its receptor TrkB, reduce IL-1β, IL-6, and TNF-α expression to treat depression." (PMID 32009949, 2019). "That is, it remains unclear whether TNF-α increases or decreases the serotonin activity in patients with depression." (PMID 31561419, 2019). "In addition, the clinical evidence suggests increased pro-inflammatory markers in patients with depression (increased TNF-α, CRP, and IL-6)." (PMID 31258489, 2019). "Only one previous investigation examined the TNF-α SNP in association to interpersonal stress and depression, and found no moderating role of the TNF-α SNP." (PMID 30967802, 2019). "Because the etiology of depression is increasingly recognized as immune activation through secretion of proinflammatory cytokines, such as IL-1, IL-6, TNF-α, IFN-γ, leukotrienes, and prostaglandins, anti-neuroinflammatory activity has been proposed by many as a potential treatment for depression." (PMID 31251788, 2019). "Furthermore, patients with polymorphic genotypes in TNF-α rs1799724 (C/T +T/T) and rs361525 (G/A+A/A) SNPs had anemia, depression, or other skin diseases." (PMID 31001258, 2019). "In the multivariate model, the change in leptin levels over time was significantly associated with the total MFSI‐SF score (β = −0.15, P = 0.003) after adjusting for the tumour necrosis factor‐α (TNF‐α) level, anxiety, depression, insomnia, age, menopausal status and type of chemotherapy." (PMID 31016867, 2019). "In this regard, the GG genotype of the TNF-α SNP, rs1800629, was associated with increased risk for suicide attempts among patients with major depressive disorder, even though this TNF-α SNP was not linked to general depression and depressive symptomatology." (PMID 30967802, 2019). "Similarly, production of IL-6, IL-10, and TNF-α levels have been shown to be increased in animal models for depression using acute or restraint stress, whereas IFN-γ production was significantly decreased by restraint stress in rats." (PMID 30792669, 2019). "One of them is the NF-κB pathway, from where MAPK, JAK/STAT, JNK, or ERK may be activated; and depression-related cytokines such as tumor necrosis factor (TNF)-α, IL-1β, and IL-6 production may increase." (PMID 31491962, 2019). "For example, major depressive disorder has been associated with increased serum acute phase reactants and proinflammatory cytokines such as C-reactive protein (CRP), interleukin (IL)-6, IL-1β, and tumor necrosis factor (TNF)." (PMID 31631951, 2019).
depression (continued). "Increasing evidence have supported a cytokine hypothesis of depression and the existence of a pro- inflammatory state in patients with unipolar depression (increased serum interleukin IL-6) and bipolar depression (increased levels of IL-1, IL-6 and TNF-α)." (PMID 31671812, 2019). "Some of the inflammatory markers are considered as to be (potentially) significant for depression, e.g., the pro-inflammatory cytokines as interleukin-6 (IL-6), interleukin-1 (IL-1), and tumor necrosis factor (TNF-α), as well as the acute phase reactant protein C-reactive protein (CRP)." (PMID 31591316, 2019). "In terms of clinical studies, a large body of evidence supports the role of TNF-α in depression." (PMID 30804748, 2019). "Numerous reports point toward the effectiveness of anti-TNFα drugs for some depression patients." (PMID 30804748, 2019). "Corticosterone, IL-6, and TNF-α were highly expressed in patients with anxiety/depression." (PMID 30979031, 2019). "Therefore, in this study, we also investigated the relationship between 5-HT levels, TNF-α mRNA expression, and the comorbidity of pain and depression and the effect of FLX on these measures." (PMID 31616368, 2019). "Use of TNF-α antagonists as antidepressants may be particularly important for subpopulations of patients with treatment resistant depression that show high levels of expression of proinflammatory cytokines." (PMID 30804748, 2019). "There is emerging evidence implying that TNF-α-producing macrophages play a key role not only in the neurodevelopment but also in the pathophysiology of various neuropsychiatric conditions, including depression." (PMID 31049023, 2019). "In the general population, clinical evidence suggests an increased tendency for pro-inflammatory markers in persons with depression (increased interleukin [IL]-6, TNF-α, and CRP) relative to controls, a trend that normalizes following response to antidepressants." (PMID 30093853, 2018). "Co-expression network analysis identified distinct gene expression perturbations across maternal diagnoses, including two depression-related modules implicated in axon-guidance and mRNA stability, as well as two PTSD-related modules implicated in TNF signaling and cellular response to stress." (PMID 29791872, 2018). "Therefore, our findings and the literature presented here suggest that TNF-α –induced inflammation is critically involved in the pathogenesis of depression, and therapies targeting this inflammation can produce therapeutic benefits." (PMID 29515447, 2018). "Median concentrations of another pro-inflammatory cytokine TNF-α were highest in the Depression (1.47 log pg/mL) group, followed by the Control (1.12 log pg/mL) and Abuse (0.43 log pg/mL) groups with mostly undetectable values for the Abuse+Depression group (p<0.01)." (PMID 29894487, 2018). "In addition, many studies have also reported increased TNF-α and IL-6 levels in acute phases of mania and depression compared to the controls." (PMID 30170608, 2018). "A significant increase in plasma IL-6, IL-1β, and TNF-α concentrations, indicating the inflammatory processes in major depressive disorder, thus supporting the cytokine hypothesis of major depression, was recorded in many studies." (PMID 30533439, 2018). "It has been presumed that TNFα, through its induction of indoleamine 2,3‐dioxygenase (IDO), activates the kynurenine pathway, which is considered to be associated with inflammation and depression." (PMID 29670819, 2018). "The first clinical trial of anti-cytokine Ab on depression was performed with TNFα inhibitors." (PMID 30423923, 2018). "Likewise, a recent case-control study of inflammatory markers among subjects with perinatal depression found that a diagnosis of major depressive disorder was significantly related to increased concentrations of TNFα." (PMID 29940888, 2018).